HES5 (hes family bHLH transcription factor 5)
Diseases named in the same sentence as HES5 in open-access papers (continued):
Sharing a sentence is not in itself a finding about the gene and the disease.
leukemia (1 paper, 2013). A malignant (clonal) hematologic disorder, involving hematopoietic stem cells and characterized by the presence of primitive or atypical myeloid or lymphoid cells in the bone marrow and the blood. "To assess the effect of Hes5 restoration in leukemia cells, we transduced FUGW-Hes5 lentiviral constructs into two Hes5 methylated/silenced B cell lines REH and RS4;11, and one Hes5 expressing T cell line T-ALL1." (PMID 23637910, 2013). "5-aza-2′-deoxycytidine treatment restored Hes5 expression and decreased promoter hypermethylation in most leukemia cell lines and primary B-ALL samples." (PMID 23637910, 2013). "To determine the relationship between histone modifications and DNA methylation at the Hes5 locus, we performed ChIP assay in leukemia cell lines having different expression levels of Hes5." (PMID 23637910, 2013). "Specifically, histone deacetylation and H3K9me is also a feasible mechanism for the silencing of Hes5 in leukemia cells." (PMID 23637910, 2013). "Notch3, JAG1, Hes2, Hes4 and Hes5 were frequently hypermethylated in B leukemia cell lines and primary B-ALL, in contrast to T-ALL cell lines and patient samples." (PMID 23637910, 2013). "To further confirm the importance of epigenetic mechanisms in down-modulation of negative growth regulatory genes and tumorigenesis, we re-expressed human Hes5 in leukemia cell lines with or without Hes5 methylation." (PMID 23637910, 2013). "In general, expression of Hes5, Hes4 and Notch3 was restored in methylated leukemia cell lines treated by DAC with or without SAHA, a phenomenon associated with gene demethylation." (PMID 23637910, 2013). "Notch3 and Hes5 genes were predominantly expressed in primary T-ALL and some T cell lines but were silenced in majority of B cell leukemia and B cell lines, suggesting that Notch3 and Hes5 could be used as T cell lineage specific markers for leukemia diagnosis." (PMID 23637910, 2013). "Notch3, Hes5, Hes2, Hes4 and JAG1 genes were found frequently hypermethylated in various leukemia cell lines but not in normal controls." (PMID 23637910, 2013). "Methylation verification revealed that Notch3, Hes5, Hes2, Hes4 and JAG1 genes were frequently hypermethylated in various leukemia cell lines but not in normal controls." (PMID 23637910, 2013).
MELAS (1 paper, 2020). "However, by day 35, mRNA expressions of Notch receptor NOTCH1, NOTCH receptor ligands DLL1 and JAG1 as well as the downstream targets HEY1 and HES5 were significantly higher in day 35 MELAS compared to controls." (PMID 32170107, 2020).
metastatic tumours (1 paper, 2013). "Furthermore, we examined the expression of HES5 in paraffin embedded primary and brain metastatic tumours by Taqman PCR and found that HES5 was indeed significantly over-expressed in metastatic tumours in the brain (n = 8) compared to the primary tumours (n = 5)." (PMID 23495140, 2013).
microcephaly (1 paper, 2022). A congenital or acquired developmental disorder in which the circumference of the head is smaller than normal for the person's age and sex. "To provide a proof-of-concept for this idea, we generated a homozygous microcephaly mutation in the same isogenic HES5::eGFP reporter line used in this study." (PMID 35697781, 2022).
mucinous tumors (1 paper, 2021). "In contrast to non‐mucinous tumors, the mucinous tumors from KLN mice displayed significant up‐regulation of Notch pathway components including Hes1, Hes5, Hey1 and Hey2, but not Wnt nor Hedgehog signaling." (PMID 33439550, 2021).
nasopharyngeal carcinoma (1 paper, 2023). A carcinoma arising from the nasopharyngeal epithelium. "Changes in neurogenesis are followed by decreased expression of Notch1, NICD, and Hes5 in the context of the pathogenesis of PD, suggesting that accumulation of–synuclein may impede nasopharyngeal carcinoma (NPC) survival by impairing the Notch signaling system." (PMID 37600520, 2023).
oligodendroglioma (1 paper, 2018). A well-differentiated (WHO grade II), diffusely infiltrating neuroglial tumor, typically located in the cerebral hemispheres. "For example, reduced expression of Notch targets, namely HES1, HEY1, and especially HEY2, was seen in clinically progressed oligodendroglioma, while HES5 expression was most associated with shorter survival on multivariable analysis." (PMID 30417117, 2018).
osteoarthritis (1 paper, 2025). A noninflammatory degenerative joint disease occurring chiefly in older persons, characterized by degeneration of the articular cartilage, hypertrophy of bone at the margins and changes in the synovial membrane. "This would be in agreement with previous work demonstrating important roles of HES1 and HES5 in chondrogenesis and cartilage development and of HES1 in preclinical models of osteoarthritis." (PMID 40345585, 2025).
prostate tumour (1 paper, 2015). "Using methylation profiling in a series of multi-focal prostate tumours, we identify promoter methylation of the transcription factor HES5 as an early event in prostate tumourigenesis." (PMID 25560400, 2015). "In this model, we predict that i) HES5 expression in benign epithelial cells contributes to HES6 repression and ii) HES5 promoter methylation and silencing in prostate tumours potentiates AR activation of HES6 to start an oncogenic feed-forward transcriptional signalling network." (PMID 25560400, 2015). "The ubiquitous HES5 silencing in tumours cells may therefore potentiate (or de-repress) HES6 expression in prostate tumours." (PMID 25560400, 2015). "Indeed, we found that HES5 expression appeared to be low and showed little variation in this series of 39 prostate tumours." (PMID 25560400, 2015). "This lack of correlation may at least in part be explained by the low or absent expression of HES5 in prostate tumour samples confounding such correlative analysis." (PMID 25560400, 2015).
pterygium (1 paper, 2021). A wedge-shaped fibrovascular lesion arising from the bulbar conjunctiva and extending to the cornea. "Some of the Notch pathway genes exhibited a modest change in expression; however, HES5, which encodes a transcription factor, was highly upregulated in pterygium." (PMID 34769520, 2021). "This analysis suggests increased activity of the Notch and Wnt epithelial differentiation pathways in pterygium, and identifies HES5, WNT7B, WNT9A, and PPM1N as being specifically involved." (PMID 34769520, 2021). "Our further analysis of pathways controlled by upstream regulator TP63 suggested increased activity of the Notch and Wnt epithelial differentiation pathways in pterygium, and identified WNT7B, WNT9A, PPM1N and HES5 as likely involved." (PMID 34769520, 2021).
retinoblastoma (1 paper, 2021). A malignant tumor that originates in the nuclear layer of the retina. "This together with lack of expression of other well-known RPCs markers such as SOX2, SFRP2, HES1 and HES5, excludes RPCs as cell of origin for retinoblastoma." (PMID 34003213, 2021).
T-cell leukemia (1 paper, 2013). A malignant disease of the T-lymphocytes in the bone marrow, thymus, and/or blood. "Hes5, Notch3 and Hes4 genes were either not expressed or very weakly expressed in highly methylated B leukemia cell lines but were abundantly expressed in unmethylated T cell leukemia cell lines such as T-ALL1 and SupT1." (PMID 23637910, 2013).
tumor (28 papers, 2010 to 2025). "In a mouse model for human CRC, it was clearly shown that Hes5 expression was upregulated in tumours carrying FBW7 heterozygous mutations when compared to tumours wild-type for FBW7." (PMID 23776410, 2013). "In addition, we functionally characterized the NOTCH target HES5 and the patient-derived HES5-R31G mutation in vitro and in an orthotopic mouse model applying different oncogenic backgrounds, to dissect the role of HES5 in different tumor subgroups in vivo." (PMID 32055024, 2020). "We confirmed loss of Hes5 mRNA in the majority of tumour cells and thereby excluded the possibility that the minority of cells deleted for Ptc1 but not for RBP-J may have had a growth advantage and populated the tumour mass." (PMID 20950430, 2010). "RNAscope analysis of 3 human CPPs showed co-expression of SOX2 and NOTCH target HES5 in a small fraction of tumor cells." (PMID 40128799, 2025). "Tumor cell groups were assigned based on chromatin accessibility of genes expressed in tumor cells, including Hes5 and Sox2, whereas regulatory regions of Lmx1a and Lmx1b were accessible only in tumor cell groups." (PMID 40128799, 2025). "The protein levels of Hes5 were significantly reduced in the tumor grafts of mice treated with fidaxomicin in a dose-dependent manner in comparison with the saline control groups." (PMID 35631382, 2022). "In accordance with in vitro results, the levels of Hes5 proteins in tumor tissues were considerably decreased after mice received various doses of fidaxomicin, suggesting a possible RBPJ-dependent inhibitory mechanism of action." (PMID 35631382, 2022). "The mechanism of action of fidaxomicin against tumors was elucidated by measuring Hes5 protein levels in tumor tissues." (PMID 35631382, 2022). "Similar to that in the TKO HCC model, in a delTP53 forebrain glioma tumor mouse, NOTCH1, NOTCH2, or RBJP knockout accelerates tumor progression, in part, by the downregulation of HES5." (PMID 33003595, 2020). "NOTCH effectively induced HES5 expression and HES5 exhibited pro- and anti-tumorigenic effects in a cell-context or tumor-driver-dependent manner." (PMID 32055024, 2020). "We observed a different expression pattern of Dll4, all Notch receptors (with regional variation) and Hes5 in the tumor epithelium." (PMID 28086833, 2017). "We observed ectopic expression of Dll4, Notch2 and 4 and Hes5 in the small intestine tumor epithelium." (PMID 28086833, 2017). "The homogenous hypermethylation of the HES5 promoter across genetically heterogeneous tumour cores is consistent with this being an early event in tumourigenesis." (PMID 25560400, 2015). "The tumour cells were dissociated and the cells were infected with pSin-puro, pSin-HES5 or PLKO-shHES5 lenti virus and they were cultured in an ultra-low attachment plate." (PMID 23495140, 2013). "The distinct methylation pattern of Notch3 and Hes5 genes in primary B cell leukemia compared to T-ALL further suggest that aberrant DNA methylation occur in a tumor specific and lineage-specific fashion." (PMID 23637910, 2013). "Simultaneously, the mRNA level of Hes5 and Glast, two markers highly expressed in NSCs were also decreased, while that of Mash1, a marker up-regulated in INPs was increased in primary tumor spheres after being treated with GSI." (PMID 21342503, 2011). "As an initial step to explore this, the relative mRNA level of HES1 and HES5, two major downstream molecules of Notch signaling, in SPDCs was examined in tumor bearing mice." (PMID 20420708, 2010). "Compared with the control, SPDCs from tumor-bearing mice had higher level of HES1 and HES5, indicating that Notch signaling was activated in SPDCs of tumor-bearing mice." (PMID 20420708, 2010).
tumor (continued). "Gene expression analyses across these cell clusters confirmed that Ascl1/GFP, along with ASCL1 canonical NOTCH signaling target genes (Dll3, Notch1, Hes5) and the bHLH E-protein co-binding partners (Tcf4, Tcf12) were significantly elevated in Ascl1-OE tumor cells compared to control." (PMID 39609428, 2024). "The expression of GFP by the tumor cells indicated derivation from Hes5+ cells." (PMID 36358826, 2022). "The high dose of fidaxomicin could reduce the expression of Hes5 by 65.7%, implying that the anti-tumor activity of fidaxomicin was correlated with its possible inhibitory ability in Notch signaling." (PMID 35631382, 2022). "Our findings suggest that a high expression of SOX8, Notch4, and Hes5 could lead to tumor metastasis." (PMID 36246971, 2022). "In addition, patients with low HES5 expression exhibited a significantly lower overall survival, suggesting a tumor suppressive function in at least a subset of HCC patients." (PMID 32055024, 2020). "On the other hand, Notch target genes Hes1, Hes5 and Hey2 were expressed with a particular pattern for each gene, with higher Hes1 expression in tumor corticotropes and reduced Hes5 and Hey2 mRNA levels compared with normal pituitary glands, Hey2 being almost undetectable in ATt20 cells." (PMID 28915655, 2017). "The same members and Hes5, instead of Hes1, presented ectopic expression in the tumor parenchyma." (PMID 28086833, 2017). "Our data are consistent with an early role in prostate tumourigenesis for promoter-wide hypermethylation of HES5, supported by the very high frequency of this epigenetic change and our observation that this was a common alteration in a series of multi-focal tumours." (PMID 25560400, 2015). "In addition, we demonstrated that the patient-derived HES5-R31G mutation is non-functional, suggesting a tumor suppressive role in the affected HCC patient." (PMID 32055024, 2020). "Therefore using our cohort of cases with multiple tumour foci and matched benign samples, we found that hypermethylation at the HES5 promoter region was observed across tumour samples from all patients and in all spatially separated tumour foci from the same patient." (PMID 25560400, 2015). "RNAscope studies of 3 human CP tumors (1 grade 1 tumor, and 2 grade 2 tumors) revealed co-expression of HES5 and LMX1A in a fraction of tumor cells." (PMID 40128799, 2025). "Analysis of GSE99671 revealed significantly higher expression levels of KLK2, NRXN1, HES5, OR2W3, and HS3ST4 in normal samples compared to tumor samples." (PMID 40128298, 2025). "Specifically, hepatocytes at the tumor periphery predominantly expressed TFs such as ILF2, ATF7, and RFXANK, while those in the tumor core were enriched for KLF4, EGR1, and HES5." (PMID 40474968, 2025). "N1IC tumor cells retained the N1IC transgene and showed increased expression of Notch downstream targets Hey1 and Hes5." (PMID 39192032, 2024). "HES5 is a key regulator of NOTCH signaling and displays context-dependent oncogenic and tumor suppressive features in liver carcinogenesis." (PMID 34944992, 2021). "We were able to demonstrate that HES5 is a key regulator of NOTCH downstream signaling in liver carcinogenesis and exhibits context-dependent oncogenic and tumor suppressive features." (PMID 32055024, 2020). "The canonical Notch target Hes5, however, which requires RBP-J, is expressed in Hh activated tumours but lost in most cells of tumours with activated Hh and inactivated Notch signalling." (PMID 20950430, 2010). "However, HES5 is also a WNT/β-catenin signaling target gene and tumor suppressor, while HES6 has been shown to be an oncogene and activator of WNT/β-catenin signaling." (PMID 32575464, 2020). "In vivo, we could show that in MYC-induced liver tumors, HES5 repressed tumor growth, whereas in AKT-induced liver tumors, HES5 promoted tumor formation." (PMID 32055024, 2020).
tumor (continued). "All of the eight GBM tissues displayed higher expression levels of HES5 mRNA along with lower levels of RND3 mRNA compared to the corresponding tumor ABTs, indicating a strong negative correlation between RND3 expression and HES5 transcript levels." (PMID 26108681, 2015). "Finally, loss of Notch1 in tumor cells did not affect the protein expression of Notch2, Jag1, and BEC marker Sox9 as well as mRNA levels of Notch targets, including Hes5 and Hey2." (PMID 29545603, 2018).
cancer (19 papers, 2010 to 2025). A tumor composed of atypical neoplastic, often pleomorphic cells that invade other tissues. "Metastatic cancer cells prompt astrocytes to increase the Jagged1 expression, which activates NOTCH signaling in cancer stem-like cells, leading to the production of HES5, a protein vital for cancer stem cell self-renewal and proliferation." (PMID 39858080, 2025). "Accordingly, the resulting paracrine interaction between Jagged1 + astrocytes and cancer cells was able to increase the stem-like phenotype in cancer cells via the Notch-Hes5 pathway." (PMID 29312881, 2017). "HES5 show direct interaction with notch signalling pathway and its dysregulation may lead to transcriptional disruption which could increase genomic instability and further cancer progression." (PMID 30212456, 2018). "Other molecules, such as FOXA1, SETD2, Hes5, C/EBP-δ, PRMT5, METTL3, Piwil1, PLK1, ERK1/2, and a series of miRNA, indirectly modulate the sensitivity of cancer cells to drugs by regulating FBXW7." (PMID 36998461, 2023). "Hes‐1 and Hes‐5 are known downstream effectors of NOTCH signaling and their expression levels are highly upregulated in a range of cancer types." (PMID 33822486, 2021). "Inhibition of Notch1 reduces cancer stem cell function, reduces expression of Notch target genes HES1, HES5 and HEY-L, and reduces the population of CD44HiCD24low, a population identified as cancer stem cells." (PMID 28594912, 2017). "Expression of HES1 and HEY1 was rather enhanced in cancer tissues, reaching significance for HES1, whereas HES5 was unchanged." (PMID 25167871, 2014). "Notch1 signaling is increased in a variety of cancers and activates downstream target genes, including HES1, HES5, DTX1, NRARP, and c-MYC." (PMID 20161710, 2010). "Notably, the NPC/GPC-like cancer cells are marked by ASCL1 or its direct target genes (DLL3, HES5) and are resistant to TMZ treatment." (PMID 39609428, 2024). "Recently, it has been shown that an antibody against the negative regulatory region (NRR) of Notch1 resulted in reduced proliferation, restricted expression of its targets HES1, HES5, and HEY-L, reduced colony forming ability, and lessened cancer stem-like population in MDA-MB-231 cell lines." (PMID 31379945, 2019). "FBXW7 itself is transcriptionally downregulated by the NOTCH downstream effector Hes‐5, and therefore, the perturbation of the feedback regulatory loop may be held responsible for the FBXW7 haploinsufficiency as seen for NOTCH‐dependent functions in the cancer stem cells (CSCs)." (PMID 33822486, 2021).
infection (8 papers, 2017 to 2024). The state of being infected such as from the introduction of a foreign agent such as serum, vaccine, antigenic substance or organism. "Semi-quantitative RT-PCR showed an up-regulation of Notch1/NICD and Notch1 target Hes5 after ad-Myc/ad-Cre infection of the cultured adult Rosa-NICD cochlea." (PMID 31797926, 2019). "Infection by TGEV disrupted the Notch signaling for Lgr5 ISCs self-renewal and differentiation via down-regulating DII4 and Hes5 protein expression both in in vivo and in vitro." (PMID 31959773, 2020). "We first confirmed the infection efficiency and upregulation of NICD/Hes5 levels in SVZ NSCs." (PMID 29296000, 2018). "As expected, we also observed that ASFV-Δ7R infection elevated the JAK1, JAK2, and Hes5 expression level in PAM cells, but not the RNF125 and ASFV p30 expression level in comparison with those of parental ASFV-infected cells." (PMID 34517008, 2021).
HES5 also shares sentences with these, for which no sentence is quoted: depression (2 papers); acute lymphoblastic leukemia (1); benign breast disease (1); benign prostatic hyperplasia (1); bipolar disorder (1); Cerebral ischemia (1); colorectal cancer (1); epilepsy (1); gastric cancer (1); glomerular disease (1); glomerulosclerosis (1); hepatocellular carcinoma (1); holoprosencephaly (1); Huntington disease (1); imbalance (1); infantile hemangiomas (1); intrahepatic cholangiocarcinoma (1); ischemia (1); ischemia reperfusion injury (1); ischemic stroke (1); Lissencephaly (1); malignant glioma (1); mental retardation (1); microphthalmia (1); myeloma (1); neuroblastoma (1); neurodevelopmental disorder (1); non-alcoholic fatty liver disease (1); Obesity (1); plasma cell leukemia (1).
A further 5 diseases each share a sentence with HES5 in 1 paper.